SAMD4A (sterile alpha motif domain containing 4A)
Description:
Acts as a translational repressor of SRE-containing messengers.
Synonyms: hSmaug1; KIAA1053; SAMD4; SMAUG1; DKFZP434H0350; Smaug; SMG; SMGA
Tractability: No criterion of Open Targets' tractability assessment is met for any kind of drug.
Gene: Protein-coding gene on chromosome 14 (54,566,117 to 54,793,315, forward strand). Ensembl gene ENSG00000020577.
Subcellular location: Cytoplasm; Cell projection, dendrite; Synapse, synaptosome
Subcellular location (Human Protein Atlas): Cell Junctions; Cytosol
Gene Ontology:
Molecular function: protein binding; RNA binding; translation repressor activity; mRNA binding
Biological process: positive regulation of translation; nuclear-transcribed mRNA poly(A) tail shortening; negative regulation of translation; regulation of mRNA stability
Cellular component: cytosol; P-body; cytoplasm; dendrite; synapse
Genetic constraint (gnomAD): Loss-of-function variants: 32 observed, 60.28 expected, observed/expected ratio (o/e) 0.53, 90% interval 0.4 to 0.71. The upper end of that interval is the gene's LOEUF score, 0.71, which puts it in group 2 of 6, group 1 being the genes least tolerant of losing a copy. Missense variants: 789 observed, 829.44 expected, observed/expected ratio (o/e) 0.95, 90% interval 0.9 to 1.01. Synonymous variants: 355 observed, 340.79 expected, observed/expected ratio (o/e) 1.04, 90% interval 0.95 to 1.14.
Homologues: Orthologues: chimpanzee SAMD4A (99% identical), macaque SAMD4A (98% identical), pig SAMD4A (97% identical), mouse Samd4 (95% identical), guinea pig SAMD4A (95% identical), rat Samd4a (94% identical), dog SAMD4A (93% identical), rabbit SAMD4A (88% identical), tropical clawed frog samd4a (80% identical), zebrafish samd4a (66% identical), Drosophila melanogaster smg (26% identical), Caenorhabditis elegans ZC190.4 (20% identical). Paralogues in human: SAMD4B (62% identical).
Diseases named in the same sentence as SAMD4A in open-access papers:
SAMD4A is named in the same sentence as 41 diseases in open-access papers, as found by Europe PMC text mining. Sharing a sentence is not in itself a finding about the gene and the disease. The quoted sentences say what the papers report.
breast carcinoma (9 papers, 2005 to 2025). "Specifically, the expression of SAMD4A is significantly reduced in human breast cancer tissues, and the low expression is associated with the poor survival of breast cancer patients." (PMID 36732864, 2023). "SAMD4A has been linked to angiogenesis and tumor progression in breast cancer, and its low expression in human breast tumor tissues/cells has been linked to a poor prognosis and survival." (PMID 36066672, 2022). "The results showed that the SAMD4B mRNA expression level was significantly higher in breast cancer tissues than in normal breast tissues, contrasting with the previously reported low SAMD4A expression in breast cancer." (PMID 41154652, 2025). "A recent research work demonstrated that SAMD4A expression is downregulated in breast cancer, where it functions as a tumor suppressor to inhibit breast tumor angiogenesis." (PMID 41154652, 2025). "A previous study has identified SAMD4A as a tumor suppressor that is downregulated in breast cancer." (PMID 41154652, 2025). "Previous studies have established SAMD4A as a tumor suppressor that is downregulated in breast cancer, while the function of SAMD4B in tumorigenesis remains poorly defined." (PMID 41154652, 2025). "For instance, SAMD4A is downregulated in breast cancer, and its upregulation inhibits breast cancer progression and angiogenesis." (PMID 41154652, 2025). "For instance, it is found that SAMD4 is highly expressed in ovarian cancer and SAMD4B is also highly expressed in colorectal cancer, while SAMD4A is low expressed in breast cancer and SAMD4A is also correlated to the development of oral cancer." (PMID 36732864, 2023). "In this study, our risk model based on TIPARP, SAMD4A, TSEN54, GSPT2, and RNASE1 was compared with the high and low risk groups of breast cancer cell lines in the CellMiner database." (PMID 36911389, 2023). "Recent studies have found that human SAMD4A acts as a novel breast cancer angiogenesis inhibitor." (PMID 36732864, 2023). "Collectively, these observations suggest that SAMD4A may be a novel breast tumor suppressor and a promising antiangiogenic target for breast cancer therapy." (PMID 36732864, 2023). "Consistent with the trend of results from public databases, TSEN54 was upregulated in breast cancer cell lines and GSPT2, RNASE1, SAMD4A, and TIPARP were downregulated in breast cancer cell lines." (PMID 36911389, 2023). "Next, we confirmed the significantly downregulated mRNA expression of AJUBA, WTIP, SAMD4A, and NOCT and moderately increased expression of PNRC1 in YAP/TAZ knockdown HCT116 cells by qPCR analysis; this pattern was also observed in A549 lung cancer cells and MDA-MB-231 breast cancer cells." (PMID 39046443, 2024). "GSPT2, SAMD4A, and TIPARP are downregulated in ECM-receptor interaction pathways, which play important roles in tumor shedding, adhesion, degradation, motility, and proliferation and may be involved in breast cancer development." (PMID 36911389, 2023).
breast tumor (6 papers, 2022 to 2025). "Low expression of SAMD4A in human breast tumor tissues and cells was also linked to a poor prognosis." (PMID 36066672, 2022). "On the contrary, knockdown of SAMD4A increases the mRNA stability of these proangiogenic genes and promotes breast tumor angiogenesis and progression." (PMID 36732864, 2023). "SAMD4A is a novel breast tumor suppressor, significantly inhibiting breast tumor-induced angiogenesis by disrupting the balance of angiogenesis-related genes in tumor cells." (PMID 36911389, 2023). "It was reported that human SAMD4A could serve as a newly identified breast tumor angiogenesis inhibitor through regulating the balance of angiogenesis program." (PMID 37904675, 2023).
colorectal cancer (3 papers, 2018 to 2024). A primary or metastatic malignant neoplasm that affects the colon or rectum. "Mechanistically, both transcriptional activation of the P-body-related genes SAMD4A, AJUBA, and WTIP and transcriptional suppression of the tumor suppressor gene PNRC1 are involved in enhancing the effects of YAP/TAZ on P-body formation in colorectal cancer (CRC) cells." (PMID 39046443, 2024).
Obesity (2 papers, 2017 to 2021). Accumulation of substantial excess body fat. "In race/ethnic-specific analyses, we identified a number of genes related to obesity (GNPDA2, ZNF664-FAM101A, PFKP, SAMD4A), glycosylation (GYPC, FUT10), and carbohydrate metabolism (GNPDA2, PFKP, SLC45A)." (PMID 28521775, 2017).
osteosarcoma (2 papers, 2020 to 2022). A usually aggressive malignant bone-forming mesenchymal neoplasm, predominantly affecting adolescents and young adults. "Although studies about the function of SAMD4A in cancer are still rare, we believe that SAMD4A will become a novel biomarker for predicting the prognosis of osteosarcoma based on the findings of this study." (PMID 33195283, 2020). "As recently reported in the case of SAMD4A knockdown in osteosarcoma epithelial cells, defects in the formation of SAMD4A-mediated proteinaceous MLOs sequestering mRNAs lead to failures in mRNA repression and a release of unnecessary mRNAs that triggers inopportune protein translation." (PMID 36274854, 2022). "Furthermore, AMN1 and ZP3 may be protective factors in osteosarcoma (HR: 1.26e−36 and 1.13e−07, respectively), whereas LIMS1, SAMD4A, and SPARC appear to be harmful factors in this setting (HR: 699.2, 167, and 298.7, respectively)." (PMID 33195283, 2020).
ovarian carcinoma (2 papers, 2023 to 2025). A malignant neoplasm originating from the surface ovarian epithelium. "For example, SAMD4A showed elevated expression in topotecan-resistant ovarian cancer cell lines and correlates with tumor chemoresistance." (PMID 41154652, 2025).
Azoospermia (1 paper, 2022). Absence of any measurable level of sperm,whereby spermatozoa cannot be observed even after centrifugation of the semen pellet. "Profiling of gene expression in human testis samples revealed that the SAMD4A expression was comparable between obstructive azoospermia patients and normal controls, but significantly lowered in nonobstructive azoospermia (NOA) patients." (PMID 36274854, 2022). "Furthermore, this study provides spermatid-specific SAMD4A as a candidate biomarker for categorizing subgroups of non-obstructive azoospermia patients." (PMID 36274854, 2022).
colon cancer (1 paper, 2021). "Further analysis revealed that ZC3H10, SAMD4A, and ENOX1 are closely related to anti-tumour immunity against colon cancer." (PMID 35155186, 2021).
Duchenne muscular dystrophy (1 paper, 2011). Duchenne muscular dystrophy (DMD) is a neuromuscular disease characterized by rapidly progressive muscle weakness and wasting due to degeneration of skeletal, smooth and cardiac muscle. "AGEP analysis of 10 Duchenne muscular dystrophy (DMD) samples provided quantitative description of the key pathogenetic events, such as the extent of inflammation, in individual samples and pinpointed tissue-specific genes whose expression changed (SAMD4A) in DMD." (PMID 21453538, 2011).
gastric cancer (1 paper, 2025). A primary or metastatic malignant neoplasm involving the stomach. "Knockdown of SAMD4A inhibited cell proliferation, invasion, and migration abilities of gastric cancer cells." (PMID 40425760, 2025). "In gastric cancer, SAMD4A plays a vital role and serves as a negative prognostic marker." (PMID 40425760, 2025).
heart failure (1 paper, 2022). Inability of the heart to pump blood at an adequate rate to meet tissue metabolic requirements. "All 14 RBPs differentially expressed between heart failure and healthy adult heart were also significantly differentially expressed between iPSC-CVPC and healthy adult heart, although three had opposite directions of effect (HNRNPL, MBNL1, SAMD4A)." (PMID 35226669, 2022).
male infertility (1 paper, 2022). The inability of the male to effect fertilization of an ovum after a specified period of unprotected intercourse. "Further understanding the molecular role of SAMD4A will advance our knowledge on genetic regulations in male infertility." (PMID 36274854, 2022). "Although male infertility was reported in chemically induced-homozygous mutation of Samd4a, there was no actual data presented to support this." (PMID 36274854, 2022).
viral infection (1 paper, 2018). "Hsa-miR-150-5p was linked to the greatest number of mRNA targets (sixteen), including SOCS1, SAMD4A, and IFIT5, which were part of previously published gene expression signatures for viral infection." (PMID 30619110, 2018).
cancer (9 papers, 2014 to 2024). A tumor composed of atypical neoplastic, often pleomorphic cells that invade other tissues. "Recent studies have indicated that SAMD4A and SAMD4B expressions are significantly changed in some types of cancers and associated with cancer progression." (PMID 36732864, 2023). "Three other genes, IFIH1, MYOT and SAMD4A, that were found to be overexpressed in the Top-resistant cell lines were not previously reported to be related to drug resistance or even to any cancer." (PMID 28611294, 2017). "Data mining for 5′-end CpG island methylation of TUSC3, ATRNL1, POMT1 and SAMD4A in cancer cell lines and primary tumors showed that the epigenetic defect was commonly observed among different tumor types in association with the diminished expression of the corresponding transcript." (PMID 30018746, 2018). "Through ENCORI database with the specific condition (strict stringency; 10 cancer types), three possible mRNAs were observed to be shared by miR-362-5p and miR-500b-5p, which were RNF145, SAMD4A (sterile alpha motif domain containing 4A) and ATP2B4 (ATPase plasma membrane Ca2+ transporting 4)." (PMID 35365168, 2022). "The occurrence of TUSC3, ATRNL1, POMT1 or SAMD4A promoter CpG island hypermethylation was not a restricted in vitro phenomenon of long-cultured cancer cell lines." (PMID 30018746, 2018).
tumor (8 papers, 2014 to 2025). "We found that SAMD4A expression was significantly downregulated in tumor tissues of patients with LUSC in the GEPIA-LUSC dataset." (PMID 40425760, 2025). "The results showed that SAMD4A acted as a tumor suppressor in LUSC by decreasing the expression of LSM12." (PMID 40425760, 2025). "SAMD4A is downregulated in the tumor tissues of LUSC in comparison to normal tissue." (PMID 40425760, 2025). "The targeted genes, ENOX1, NCAM1, SAMD4A, and ZC3H10, are closely related to CRC tumour-infiltrating macrophages." (PMID 35155186, 2021). "Significant correlation was observed between the polarised M2 macrophages and ENOX1, NCAM1, SAMD4A, and ZC3H10 with respect to tumour purity." (PMID 35155186, 2021).
myopathy (3 papers, 2013 to 2024). A disease of the muscle in which the muscle fibers do not function properly. "Loss of SAMD4A has been linked to changes in RNA-binding and post-transcriptional regulation that can exacerbate myopathy and cause metabolic defects such as uncoupling of mitochondrial respiration." (PMID 37856562, 2024). "Conversely, decreased levels of SAMD4A aggravates the myopathy phenotype induced by CUG and restores muscle function." (PMID 36732864, 2023). "Meanwhile, increased levels of human SAMD4A in myoblasts from DM1 patients restores the translation activity of CUGBP1, and thus inhibiting CUG-induced myopathy through physically interacting with CUGBP1." (PMID 36732864, 2023).
SAMD4A also shares sentences with these, for which no sentence is quoted: lung carcinoma (2 papers); acromelic dysplasia (1); colon adenocarcinoma (1); diabetes (1); Esophageal Carcinoma (1); Head-Neck Squamous Cell Carcinoma (1); hearing loss (1); hematological malignancies (1); Hepatic steatosis (1); Insulin resistance (1); Lassa virus infection (1); leukemia (1); liver fibrosis (1); lymphoma (1); metabolic disorders (1); myocardial infarction (1); myotonic dystrophy type 1 (1); neurodegenerative disease (1); oral cancer (1); osteoporosis (1); pancreatic cancer (1); prostate carcinoma (1); rectum adenocarcinoma (1); rheumatic disease (1); Stomach Adenocarcinoma (1).